FOXO1 (forkhead box O1)
Diseases named in the same sentence as FOXO1 in open-access papers (continued):
Sharing a sentence is not in itself a finding about the gene and the disease.
glioma (continued). "Compared with nor-tumor brain tissue samples, FOXO1 protein level was significantly down-regulated in the majority of primary glioma tissue samples, with a greater decrease in high-grade gliomas than in low-grade." (PMID 27835585, 2016). "Given that FOXO1 inhibits glioma cells invasion and growth, and that KLF4 transcriptionally inhibits FOXO1 expression, we here also observed the effects of KLF4 on invasion and growth in glioma cells." (PMID 27835585, 2016). "Under metabolic stress, FOXO1 increases Cyclin F but not other Cyclins in gliomas, suppressing IDH1 expression, an essential tumor marker which its overexpression is implicated in glioma progression." (PMID 37821870, 2023). "These investigations indicated a negative correlation between KLF4 and FOXO1 in gliomas." (PMID 27835585, 2016). "In more detail, the binding of FOXO1 but not FOXO3a, FOXO4, or FOXO6 to cyclin F promoter subsequently represses the expression of IDH1 as a crucial proto-oncogene in glioma." (PMID 37821870, 2023). "Similarly, increased TIM-3 expression and decreased IFNγ expression were demonstrated in tumor-infiltrating CD8+ T cells in a syngeneic glioma mouse model, although potential changes in BAT3, FOXO1, BLIMP1, and CD69 expression were not reported in this study." (PMID 39513882, 2024).
Hepatic steatosis (46 papers, 2012 to 2025). Steatosis is a term used to denote lipid accumulation within hepatocytes. "It has been reported that FoxO1 improves hepatic insulin signaling and fatty liver disease, although the underlying mechanisms remain to be elucidated." (PMID 31246177, 2019). "Recent study shows that prompting APN and inhibiting the activation and expression of forkhead box protein O1 (FoxO1) is associated with attenuation of hepatic steatosis in high-fat- and high-sugar-treated rats." (PMID 30186875, 2018). "Understanding the mechanisms of FoxO1 action is of great importance as it may allow for the identification of new therapeutic targets for age-associated hepatic steatosis." (PMID 31246177, 2019). "A previous study has extensively investigated the role of FOXO1 in glucose metabolism, cell behavior, and susceptibility to infection, implicating its involvement in the pathogenesis and progression of various diseases, such as cancer, liver steatosis, and atherosclerosis." (PMID 38556884, 2024). "Methyl ferulate downregulates the phosphorylated expression of p38 Mitogen-Activated Protein Kinase (p38 MAPK), c-Jun N-Terminal Kinase (JNK), Extracellular Signal-Regulated Kinase (ERK), and FoxO1 in L-02 cells, inhibiting ethanol-induced hepatic steatosis." (PMID 41154556, 2025). "Endoplasmic reticulum stress induces hepatic steatosis through FoxO1, which stimulated the up-regulation of PPAR γ." (PMID 40427649, 2025). "Molecular biology and biochemical research has indicated that the C-terminal region of Kindlin-2 binds to Foxo1 and inhibits Skp2-mediated ubiquitination of the Foxo1 protein, enhancing Foxo1 protein stability and inducing hepatic steatosis." (PMID 40292292, 2025). "Concerning the effects of n-3 PUFA on Foxo1, eicosapentaenoic acid (EPA) supplementation decreased hepatic steatosis and lowered hepatic FOXO1 protein expression in young Zucker rats." (PMID 39264516, 2024). "Ubiquitination-mediated degradation of FOXO1 has been shown to inhibit lipid accumulation in hepatic cells, thus playing a protective role against fatty liver." (PMID 39021599, 2024). "The overexpression of FOXO1 in liver contributes to an increase in the synthesis of triglyceride (TGs) and a decrease in the oxidation of fatty acids, exacerbating hepatic steatosis." (PMID 38459489, 2024). "Taken together, these results suggest that Notch1 signaling is essential for the Foxo1-mediated regulation of hepatic steatosis, inflammation, and fibrosis in macrophages during NASH progression." (PMID 39122845, 2024). "When challenged with HFD-specific FOXO1/3/4, knockout mice have a phenotype with very severe hepatic steatosis, as well as severe inflammation and fibrosis, especially in response to a high-fat plus cholesterol diet." (PMID 35222075, 2022). "This lncRNA negatively regulates the expression of Atgl and promotes hepatic steatosis via the suppression of fork-head box protein O1 (Foxo1) and Pparg which promotes the transactivation of the Atgl enzyme." (PMID 35052690, 2021). "We therefore examined the role of FoxO1 as a downstream suppressor to palmitate-stimulated hepatic steatosis." (PMID 33449950, 2021). "The overexpression of FoxO1 in the liver leads to a rise in triglyceride (TG) synthesis and a decline in fatty acid oxidation, aggravating liver steatosis." (PMID 33804729, 2021). "Specifically, the deletion of FOXO1/3 or FOXO1/3/4 genes in mouse livers leads to mild or moderate hepatic steatosis, even when mice are maintained on a regular chow diet." (PMID 32660130, 2020). "It is known that FoxO1 and PPARγ are closely associated with hepatic steatosis and our study provides additional evidence that ER stress induces hepatic steatosis through FoxO1-induced PPARγ upregulation." (PMID 31246177, 2019). "Although various studies reported that both FoxO1 and PPARγ stimulated hepatic steatosis, the functional relationship between these two proteins in the context of aging is unclear." (PMID 31246177, 2019).
Hepatic steatosis (continued). "We used the AC2F liver cell line to further investigate the functional role of FoxO1 in hepatic steatosis." (PMID 31246177, 2019). "Our data from the Foxo1/3/4-LTKO mice indicate that deletion of FOXO1/3/4 genes exacerbates diet-induced hepatic steatosis and liver injury, suggesting a protective role of FOXOs in the liver." (PMID 28300161, 2017). "The lncRNA SRA (steroid receptor RNA activator) was shown to promote hepatic steatosis via repression of adipose triglyceride lipase (Atgl) by inhibiting transcriptional activity of forkhead box protein O1 (FoxO1)." (PMID 29189723, 2017). "FoxO1 is a member of the FoxO family and plays an important role in hepatic steatosis." (PMID 41154556, 2025). "Moreover, lncRNAs can regulate lipid metabolism to influence fat deposition, for example, the lncRNA-SRA limits adipose triglyceride lipase promoter activity in hepatic steatosis primarily by inhibiting forkhead box protein O1 (FoxO1) expression." (PMID 41375517, 2025). "Interestingly, HFD-induced oxidative stress activated STING signaling, whereas macrophage Foxo1 deficiency inhibited STING function and was accompanied by reduced hepatic steatosis, fibrosis, and inflammation in steatotic livers." (PMID 39122845, 2024). "To determine whether macrophage Foxo1 is involved in hepatic steatosis, we examined Foxo1 expression in Kupffer cells from steatotic livers." (PMID 39122845, 2024). "However, some studies show that inhibition of Foxo1 interacts with ATGL leading to hepatic steatosis." (PMID 37033250, 2023). "However, simultaneous deletion of FoxO1 and FoxO3 revealed a synergistic increase in the transcription of the lipogenic enzyme glucokinase (Gck), which lead to hepatic steatosis." (PMID 37941908, 2023). "Here, myeloid-FATP4 deficiency may promote male-prone abnormalities by exacerbating hepatic steatosis possibly via the strong activation of PPARγ, CEBPα, and p-FoxO1 in their Kupffer cells." (PMID 36881564, 2023). "FOXO1 inhibition by AS1842856 attenuates hepatic steatosis in diet‐induced obesity mice." (PMID 37602516, 2023). "Notably, FOXO1/3 or FOXO1/3/4 genes knockout in mouse liver, respectively, resulted in a mild or moderate hepatic steatosis on a standard chow diet." (PMID 35222075, 2022). "Thus, liver FoxO1-null mice developed hepatic steatosis, accompanied by the upregulation of lipogenic genes." (PMID 33105604, 2020). "Here, we examined the molecular mechanism by which FoxO1 ameliorates hepatic steatosis in aging." (PMID 31246177, 2019). "In addition, the interaction between FoxO1 and PPARγ was shown to induce hepatic steatosis in aging and db/db mice." (PMID 31235676, 2019). "This regulation may involve the control of gluconeogenesis and a reduction of hepatic steatosis through the FoxO1/PGC-1α pathway." (PMID 31853220, 2019). "The present study indicated that inhibition of FoxO1 may have therapeutic benefits for chronic stress relative fatty liver disease." (PMID 31579588, 2019). "The Chinese herbal extract QSHX inhibits FOXO1 signaling activation to increase the expression of DsbA-L and HMW APN, thereby significantly reducing hepatic steatosis and damage in MAFLD rats." (PMID 39021599, 2024). "Disruption of macrophage Foxo1 increased PCG-1α, promoted the YAP–NICD interaction, and ameliorated hepatic steatosis and inflammation in NASH patients." (PMID 39122845, 2024). "Using the generated myeloid Foxo1 and YAP double-KO (Foxo1/YAPM-DKO) mice, we found that Foxo1M-KO decreased lipid accumulation, whereas Foxo1/YAPM-DKO resulted in increased hepatic steatosis after 24 weeks of HFD feeding." (PMID 39122845, 2024). "FOXO1 inhibition by AS1842856 significantly alleviated glucose intolerance, hepatic steatosis, and systemic inflammation in old mice." (PMID 37602516, 2023). "It has been found that the activity and expression of Foxo1 in liver are upregulated in NASH patients, from simple fatty liver to nonalcoholic steatohepatitis." (PMID 32429849, 2020).
Hepatic steatosis (continued). "Methyl FA could inhibit lipid synthesis through AMPK and FoxO1 signal pathways while promoting lipid oxidation via the SIRT1/PPAR-α/CPT-1α axis, ultimately attenuating ethanol-induced hepatic steatosis." (PMID 39594419, 2024). "Acting as a deacetylase of FOXO1, HDAC6 is downregulated by binding to S100A11, which increases the acetylation and activity of FOXO1, leading to lipogenesis and activation of autophagy in the liver, thus exacerbating liver steatosis." (PMID 36864020, 2023). "In addition, FOXO1 induces the transcription of genes involved in the hepatic assembly of VLDL, reducing hepatic steatosis." (PMID 32660130, 2020). "In our present study, the decreased protein level of SIRT1 and its activity, as evidenced by increased acylated-FOXO1, resulted in the increased proteins level of ACC and SCD1, which supported the role of SIRT1 in mediating hepatic steatosis induced by HCLD feeding." (PMID 26608583, 2015).
atherosclerosis (44 papers, 2014 to 2025). A disease characterized by the build-up of fatty material and calcium deposition in the arterial wall resulting in partial or complete occlusion of the arterial lumen. "The association between FOXO1 expression level and features of atherosclerosis has been reported by several studies." (PMID 36289866, 2022). "METTL14 promotes inflammatory responses in atherosclerosis-associated macrophages through NF-κB/IL-6 signaling pathway and also increases m6A modification of forkhead box O1 (FOXO1), thereby increasing adhesion molecule expression, mediating endothelialmonocyte adhesione." (PMID 40662138, 2025). "As a downstream regulator of the PI3K/AKT pathway, FOXO1 participates in the regulation of the cardiovascular system in a variety of diseases, such as hypertension, cardiac hypertrophy, and atherosclerosis." (PMID 40406487, 2025). "Myeloid-specific FoxO KO (FoxO1, FoxO3a, and FoxO4), which was elevated in atherosclerotic mice’ macrophages, surprisingly worsened atherosclerosis by stimulating bone marrow cell growth." (PMID 40141412, 2025). "For instance, the overexpression of METTL14 in endothelial cells is responsible for monocyte aggregation, via affecting either the m6A levels of FoxO1 mRNA or the binding affinity of the FoxO1 protein, resulting in the progression of atherosclerosis." (PMID 36768716, 2023). "We show that deletion of Tie2, or both Tie2 and Tie1, in the arterial endothelium promotes atherosclerosis by increasing Foxo1 nuclear localization, endothelial adhesion molecule expression and accumulation of immune cells." (PMID 37476204, 2023). "Our findings also suggest that the GM-CSF receptor/SYK/JNK/FOXO1/CD11c signaling axis is commonly involved in the development of atherosclerosis and chronic inflammation." (PMID 37520709, 2023). "Third, although AS1842856 specifically suppresses FOXO1, it cannot be excluded that the off-target effect of FOXO3a inhibition contributes to atherosclerosis suppression." (PMID 37520709, 2023). "In a previous study, endothelium-specific FOXO isoform (FOXO1, 3a, and 4) triple-knockout mice exhibited atherosclerosis alleviation via enhanced nitric oxide availability, inflammation, and superoxide generation." (PMID 37520709, 2023). "Our study revealed that in patients with β-TM, an increment in FOXO1 and HSP72 signaling with low levels of SIRT1 is linked to accelerated atherosclerosis, which is crucial as a novel biomarker for the prediction of atherosclerosis." (PMID 36289866, 2022). "FoxO1 is highly expressed in atherosclerotic plaques and appears to have an atheroprotective effect since FoxO1 knockdown in endothelial cells in a mouse model reduced atherosclerosis." (PMID 35607519, 2022). "Combined with the report that SIRT1/FoxO1 pathway enhances autophagy flux in order to prevent atherosclerosis and arterial thrombosis, we believe SIRT1 plays a critical role in DMC." (PMID 35508613, 2022). "Our findings confirmed that METTL14 can enhance its translation by increasing m6A modification on FOXO1, thereby increasing adhesion molecule expression, mediating endothelial-monocyte adhesion, and participating in atherosclerosis development." (PMID 32802173, 2020). "Endothelial FOXO1 deletion has been shown to prevent atherosclerosis and elevate the number of skeletal muscle capillaries in studies in vivo." (PMID 33028948, 2020). "FOXO1 is strongly expressed in atherosclerotic plaques and shows atheroprotective effect, as FOXO1 silencing in endothelial cells prevented atherosclerosis in mouse model." (PMID 31146723, 2019).
atherosclerosis (continued). "In summary, this finding states the vital role of the circCHFR/miR-370/FOXO1/Cyclin D1 axis and provides a profound understanding about the circRNA in smooth muscle cells and atherosclerosis." (PMID 31048182, 2019). "Furthermore, investigating downstream targets of FoxO1/pFoxO1 and validation should also be evaluated in vivo models of atherosclerosis and vascular diseases in the future." (PMID 40046255, 2025). "Furthermore, our study outcomes indicate that metformin reduces FABP4 expression, thereby limiting the nuclear translocation of FOXO1 in atherosclerosis." (PMID 41471323, 2025). "Furthermore, another m6A writer, METTL14, was reported to increase the translation of Foxo1 and aggravated endothelial inflammation and atherosclerosis." (PMID 37486903, 2023). "Moreover, AS1842856, a FOXO1 inhibitor, reduced atherosclerosis by decreasing CD11c expression, indicating its therapeutic potential." (PMID 37520709, 2023). "A recent study has demonstrated that FOXO1 m6A methylation could promote its mRNA expression and the development of endothelial cell inflammation and atherosclerosis." (PMID 38097926, 2023). "Further investigation is needed to determine whether the suppression of FOXO1 could alleviate atherosclerosis in SLE patients." (PMID 37520709, 2023). "As both Tie receptors can be modulated via their extracellular domains that are available in vessel lumen, they provide vascular targets for counteracting inflammation via Foxo1 transcriptional activity, and hopefully eventually for treatment of atherosclerosis." (PMID 37476204, 2023). "Furthermore, the function of each isoform differs in different organs; notably, skeletal muscle-specific FOXO1 overexpression in ApoE−/− mice suppresses atherosclerosis." (PMID 37520709, 2023). "The FOXO1 inhibitor notably suppressed atherosclerosis in the aortic sinus and aorta." (PMID 37520709, 2023). "Hence, increments of FOXO1 and its gene expression in β-TM patients are suggested to be a marker of atherosclerosis, as FOXO1 deacetylation can lead to atherosclerotic plaque formation due to endothelial tissue dysfunction in arteries." (PMID 36289866, 2022). "Moreover, FOXO1 silencing in mouse endothelial cells prevented atherosclerosis, and indicates that FOXO1 is an atheroprotective molecule." (PMID 31146723, 2019). "Until now, the roles of SIRT1 and FOXO1 in atherosclerosis as therapeutic target remain largely unknown." (PMID 31146723, 2019). "The genetic effect of SIRT1 and FOXO1 on common carotid IMT shown in the current study might be explained by their direct involvement in the pathophysiological mechanisms of atherosclerosis." (PMID 25273948, 2014). "Taking into consideration that atherosclerosis is an aspect of the aging process we hypothesized that genetic polymorphisms at SIRT1 and FOXO1 may also play a role in carotid atherosclerosis." (PMID 25273948, 2014). "Furthermore, FOXO1 inhibitor treatment mitigated atherosclerosis in mice." (PMID 37520709, 2023). "Thus, GM-CSF receptor/SYK/JNK/FOXO1/CD11c signaling in monocytes and macrophages and FOXO1 could be therapeutic targets for atherosclerosis and inflammatory diseases." (PMID 37520709, 2023). "Hence, our results confirmed that METTL14 may inhibit atherosclerosis development by regulating FOXO1 expression in mice." (PMID 32802173, 2020). "Conversely, downregulation of FABP4 by apelin/apelin receptor (APLNR)-mediated Forkhead box O1 (FOXO1) suppression in ECs limits excessive FA transport and tissue accumulation, contributing to atheroprotecton against vascular diseases such as atherosclerosis." (PMID 40890841, 2025).